AR (androgen receptor)
Diseases named in the same sentence as AR in open-access papers (continued):
Sharing a sentence is not in itself a finding about the gene and the disease.
prostatic hyperplasia (34 papers, 2010 to 2025). "Our data provide new insights into the mechanisms underlying AR functions in inflammation/cell death in prostate disease." (PMID 29050220, 2017). "Previous studies have reported that the activity of NF-κB promotes the continuous transcription of proliferative genes by maintaining the activity of the AR, which has central roles in the progression and development of prostate disease." (PMID 34073143, 2021). "The role of AR is to enhance cell proliferation and survival of glandular epithelium of the prostate, such that its overexpression contributes to progression of prostate diseases." (PMID 32018227, 2020). "As 5AR is the initial trigger of prostatic hyperplasia and AR is the main receptor related in it, these results suggest a pharmaceutical potential of CA on BPH treatment." (PMID 27880726, 2017). "Because 5AR is the initial trigger of prostatic hyperplasia and AR is the main receptor in that process, these results suggest the pharmaceutical potential of VA as a therapeutic agent for BPH." (PMID 29152074, 2017). "As PI3K-Akt pathways are involved in proliferation and apoptosis in prostate through crosstalk with AR, targeting PI3K-Akt signaling pathway appears to be a promising therapeutic target in prostate disease." (PMID 41011193, 2025). "Increased expressions of AR, 5AR2, and PSA correlate with prostate hyperplasia, and these markers are increased markedly in patients and in animal models with BPH." (PMID 35715415, 2022). "Our results also showed that macrophage distribution and AR signaling of the prostate transitional zone of BPH patients were higher than those for peripheral zone, resulting in prostatic hyperplasia occurring in the transitional zone." (PMID 28694768, 2017).
bladder tumors (32 papers, 2012 to 2025). "For example, AR depletion in mouse models reduces susceptibility to chemically induced bladder tumors, highlighting the protumorigenic role of AR." (PMID 40806474, 2025). "Single-cell genomic analysis of murine bladder tumors pointed to TCF1 having AR as a target, which was an association that was thoroughly evaluated by the study group as well." (PMID 38398136, 2024). "In our meta-analysis, AR expression in NMI bladder tumors was found to associate with better recurrence-free survival [hazard ratio (HR) = 0.593; 95% CI = 0.408–0.860; p = 0.006], but not with progression-free survival (p = 0.223)." (PMID 34064926, 2021). "In the androgen deprivation cohort for which tissue specimens were available (n = 72), AR expression in de novo bladder tumors, as an independent prognosticator, was further associated with successful prevention of tumor recurrence (hazard ratio (HR) = 0.27, p = 0.005)." (PMID 32759680, 2020). "It will be important to correlate FOXA1 expression with disease specific outcome in future studies, and to determine the functional significance of FOXA1 expression for AR and ER activity, as these receptors have been implicated in the molecular pathogenesis of bladder tumors." (PMID 22590586, 2012). "Thus, additional levels of gene regulation should underlie the different AR mRNA expression levels in these two isogenic cell lines, which also could explain the differences in AR levels found in bladder tumours." (PMID 33797847, 2021). "Higher AR levels were found in bladder tumors compared to normal bladder mucosa, and they were higher in males compared to females." (PMID 41228208, 2025). "Another group used the UPII promoter to drive an E1A-androgen receptor (E1A-AR) fusion protein expression, where intratumoral injection of Ad/PSCAE/UPII/E1A-AR significantly reduced bladder tumor growth in subcutaneous mouse models." (PMID 41445946, 2025). "Several key studies have shown that AR signaling is required for bladder tumor development in different carcinogen-induced orthotopic murine models." (PMID 38398136, 2024). "Our data suggest that not only concurrent antiandrogen therapy but also GABBR2 inhibitor treatment has the potential of being a means of chemosensitization, especially in patients with AR/GABBR2-positive bladder tumor." (PMID 37762034, 2023). "Clustering based on their autosome copy number transition points assigned the two adjacent tumors to separate clusters with AR copy number matching the respective bladder tumor samples." (PMID 37563129, 2023). "In our previous study, AR was stained in the 43 bladder tumors included in the second set of TMA, showing immunoreactivity in 13 (30%) cases." (PMID 34576193, 2021). "While GULP1 activators are not currently available, our data further support the notion that concurrent anti-androgen therapy has the potential of being a means of chemosensitization, especially in male patients with AR-positive bladder tumor." (PMID 34576193, 2021). "While BXDC2 activators are not currently available, our data further support that concurrent anti-androgen therapy has the potential of being a means of chemosensitization, especially in male patients with AR-positive bladder tumor." (PMID 33652650, 2021). "Surgical castration of mice prior to carcinogen treatment also significantly reduced bladder tumour formation, and knockout of the AR gene completely prevented bladder carcinogenesis." (PMID 33797847, 2021). "In bladder tumor specimens, significant correlations between immunoreactivities to AR versus ATF2 or phospho-ATF2 were observed." (PMID 32759680, 2020). "More recently, a higher incidence of BBN-induced bladder tumors was found in transgenic male (67% vs. 23%) and female (39% vs. 0%) mice where AR was conditionally expressed in the bladder, compared with respective control littermates." (PMID 32759680, 2020). "In bladder tumor samples, the expression of AR and ELK1 or phospho-ELK1 was significantly correlated." (PMID 32759680, 2020).
bladder tumors (continued). "In most of these studies, a bladder carcinogen N-butyl-N-4-hydroxybutyl nitrosamine (BBN), which reliably induces bladder tumors, especially in male rodents, has been used along with androgen/anti-androgen treatment and/or AR knockdown." (PMID 32759680, 2020). "Immunohistochemistry showed significant correlations between p-FOXO1 expression and AR positivity in bladder tumors or ERβ positivity in UUT tumors, as well as between FOXO1 expression and ERα positivity or ERβ negativity." (PMID 32759680, 2020). "The positive rates of AR expression immunohistochemically detected in bladder tumor tissues involving more than 40 cases range from 13% to 55%, which are significantly lower than those in non-neoplastic urothelial samples in some studies." (PMID 28241422, 2017). "Initial studies examining AR expression in tissue lysates prepared from bladder tumor biopsies detected high levels of AR expression in both male and female patients when compared to samples from normal bladder urothelium." (PMID 26862755, 2016). "Taken together, our data demonstrate for the first time that conditional activation of transgenic AR expression in bladder urothelium enhances carciongen-induced bladder tumor formation in mice." (PMID 26862755, 2016). "Taken together, our data demonstrate for the first time that conditional activation of transgenic AR expression in bladder urothelium enhances carcinogen-induced bladder tumor formation in mice." (PMID 26862755, 2016). "Nonetheless, AR positivity in bladder tumors, especially in muscle-invasive carcinomas, has been associated with worse patient outcomes." (PMID 27322140, 2016). "Specifically, androgen and androgen receptor depletion protected mice from development of chemical carcinogen induced bladder tumors." (PMID 23284679, 2012). "Our in vitro data indicate that androgen/AR signalling is involved in the acquisition of a more aggressive phenotype of bladder tumour cells and that it can be reverted with blockage of AR signalling, advocating the potential benefits of AR‐targeted therapy for UCC." (PMID 33797847, 2021). "Indeed, early phase clinical trials have been conducted to assess the efficacy of AR antagonists in, for instance, the prevention of bladder tumor recurrence after transurethral surgery." (PMID 32759680, 2020). "In bladder tumors, immunoreactivity to NF-κB versus AR was significantly correlated." (PMID 32759680, 2020). "However, a subset of male ARKO mice treated with BBN and supplemented with DHT developed bladder tumors, suggesting the involvement of androgen-mediated non-AR pathways in bladder tumorigenesis." (PMID 28241422, 2017). "A chemical carcinogen, N-butyl-N-4-hydroxybutyl nitrosamine (BBN), which is known to induce a bladder tumor effectively in experimental rodents and more rapidly in male animals than in females, has been used to assess the effects of androgens, AR, and anti-AR treatment on bladder carcinogenesis." (PMID 28241422, 2017). "Similarly, the incidence of a BBN-induced bladder tumor in a transgenic mouse model where AR is conditionally expressed in the bladder urothelium was higher than that in age and sex matched controls." (PMID 28241422, 2017). "More interestingly, ELK1/p-ELK1 and AR expression in bladder tumors was positively correlated." (PMID 26342199, 2015). "Despite the promoting effects of AR signals on tumorigenesis, two studies showed a significant correlation and a tendency, respectively, between AR expression and lower risks of bladder tumor recurrence." (PMID 26770009, 2015). "In addition, several studies have demonstrated differences in the number of polyglutamine (CAG) repeats within exon 1 of the AR gene, which in general is inversely correlated with its transcriptional activity, between bladder tumors and controls or different grades/stages of bladder tumors." (PMID 28241422, 2017).
bladder tumors (continued). "On the other hand, none of previous studies have revealed a significant difference in the levels of AR expression between male versus female bladder tumors, while it remains unclear whether low levels of androgens significantly activate AR in, for instance, female tumors." (PMID 27322140, 2016). "Together, these results demonstrate the key roles of B cells within the bladder tumor microenvironment that increase the BCa metastasis and may help us to develop the potential therapies via targeting these newly identified IL-8/AR/MMPs signals to better battle the BCa progression." (PMID 26305549, 2015). "HRs of AR positivity for RFS and PFS were available in 3 and 2 studies accounting for 496 and 327 patients with NMI bladder tumor, respectively." (PMID 28362839, 2017). "Bladder tumors were absent in AR knockout mice, which underscored the pivotal role of AR in carcinogen-induced bladder carcinogenesis." (PMID 41228208, 2025). "Meanwhile, to the best of our knowledge, no studies have demonstrated the differences in AR expression in bladder tumors resected from various regions." (PMID 40486871, 2025). "There was a notable difference in AR expression in gained compared to non-gained metastases with the exception of the non-gained bladder tumor (adjacent to an area with gain suggesting the possibility of admixture of AR gained and non-gained clones)." (PMID 37563129, 2023). "In CA63, of the two biopsies from the same bladder tumor, one (CA63_3) was AR amplified and the other (CA63_2) was not." (PMID 37563129, 2023). "Miyamoto and colleagues documented that AR involving genomic or non-genomic signals can also induce bladder tumor." (PMID 31119584, 2019). "In animal studies, androgen receptor knockout (AR-KO) male mice developed fewer bladder tumors, and females without AR developed no tumors." (PMID 29725350, 2018). "Similar to the AR positivity in bladder tumors compared with non-neoplastic bladders, its significant or insignificant down-regulation is observed in high-grade and/or muscle-invasive tumors." (PMID 28241422, 2017). "Thereafter, immunohistochemical studies in surgical specimens have assessed the expression status of AR in different grades/stages of bladder tumors, in comparison with normal/non-neoplastic urothelial tissues in some of them." (PMID 28241422, 2017). "More recently, BBN was also found to fail to induce bladder tumors in male mice having normal levels of testosterone yet lacking AR specifically in the urothelium." (PMID 28241422, 2017). "Immunohistochemistry in tissue samples showed the expression of NCOA1, NCOA2, NCOA3, CREBBP, and EP300, in 85%–100% of bladder tumors—some of which even lacked AR expression." (PMID 28241422, 2017). "It has been shown that the levels of AR expression are significantly lower in bladder tumors than in non-neoplastic urothelial tissues as well as in high-grade/muscle-invasive bladder carcinomas than in low-grade/superficial tumors." (PMID 27322140, 2016). "Immunohistochemistry in bladder tumor specimens showed that the levels of phospho-ELK1 (p-ELK1) expression were significantly elevated in urothelial neoplasms, compared with non-neoplastic urothelium tissues, and were also correlated with AR positivity." (PMID 26342199, 2015). "None of androgen receptor (AR) knockout (ARKO) mice developed bladder tumors." (PMID 23752272, 2013). "They showed that ARKO (AR knockout) mice do not get chemically induced bladder carcinogenesis, but when ARKO mice were supplemented with DHT, 25% of them developed bladder tumors." (PMID 31119584, 2019). "In immunohistochemical staining in TUR specimens, LPHN3 expression was significantly up-regulated in bladder tumors, compared with non-neoplastic urothelial tissues (p = 0.028), and the expression of LPHN3 and AR in tumors was significantly correlated (p = 0.021)." (PMID 40486871, 2025).
small cell carcinoma (31 papers, 2014 to 2025). A neuroendocrine carcinoma composed of small malignant cells which are often said to resemble "oat cells" under the microscope. "In the subset of mCRPC tumors, there is a phenotypic switch from an androgen receptor signaling enhanced mCRPC to an androgen receptor signaling reduced small cell carcinoma after androgen deprivation therapy." (PMID 35508696, 2022). "It is mainly a mixture of small cell carcinoma and adenocarcinoma and also expresses neuroendocrine markers, but has a lower expression of AR and a higher expression of PSA compared to NEPC." (PMID 36118857, 2022). "Several groups found that AR-regulated TMPRSS2-ERG genomic translocation in AR-negative small-cell carcinoma also existed in AR-positive adenocarcinoma." (PMID 30248934, 2018). "Indeed, the lineage transition to a NE subtype is one mechanism by which PCa evades androgen receptor (AR)-targeting treatment by shifting its cellular phenotype from an AR-dependent adenocarcinoma to an AR-indifferent NE or small-cell carcinoma." (PMID 37455903, 2023). "A subset of CRPC may progress to lethal AR-indifferent neuroendocrine/small cell carcinoma (NE/SC) following further AR suppression by the second and third-generation AR inhibitors (e.g., abiraterone, enzalutamide, apalutamide, darolutamide)." (PMID 34884545, 2021). "Lastly, AR–/NE+ tumors (also termed neuroendocrine prostate cancer [NEPC]) lack AR but show robust NE marker expression and exhibit overlapping features with high-grade NE (small-cell) carcinomas arising in other organ sites." (PMID 40493417, 2025). "Small-cell carcinoma is the most common histology within NEPC and associated with low or absent AR and low PSA and other AR-target genes." (PMID 41056440, 2025). "These tumors are characterized by a low level or lack of AR expression, an independence of AR signaling, and a gain of neuroendocrine phenotype, often becoming AR-negative, poorly differentiated small cell neuroendocrine carcinoma." (PMID 37834162, 2023). "Prognosis for AR-negative CRPC is poor with a median survival of 12 months for AR-negative small cell carcinoma." (PMID 34944438, 2021). "That said, the treatment of confirmed AR-negative disease with neuroendocrine differentiation, the most common subtype of AR-negative mCRPC, is a platinum-based regimen similar to those employed for the treatment of other neuroendocrine small cell carcinomas." (PMID 33420371, 2021). "Around 15–20% of CRPC tumors eventually become independent of AR signaling, though detecting this shift in clinical practice remains difficult; one notable sign is the histologic progression from AR-positive adenocarcinoma to AR-negative, poorly differentiated small cell neuroendocrine carcinoma." (PMID 41373813, 2025). "Consistently, the LnNE model preserves AR protein levels but becomes PSA negative, supporting the notion that reduced AR function is concurrent with NEPC progression from adenocarcinoma with neuroendocrine differentiation to small cell neuroendocrine carcinoma." (PMID 28978002, 2017). "However, progression in the mouse to classic small cell carcinoma pathology is accompanied by weak to negative staining for the AR." (PMID 27542219, 2016). "Prostate-specific immunostains (such as PSA, p501s and PSMA) are positive in only a minority of small cell carcinoma (approximately 20–25%) AR and NKX3-1 were not expressed in the majority of small cell carcinoma, although the majority of the concurrent acinar foci were positive for these markers." (PMID 25042800, 2014).
small cell carcinoma (continued). "However, after a period of treatment, castration resistance ultimately ensues and the disease may develop into androgen receptor (AR)-castration-resistant prostate cancer (CRPC) or even neuroendocrine prostate cancer (NEPC), an AR-negative small cell neuroendocrine carcinoma." (PMID 34646778, 2021). "T-NEPC, especially small-cell carcinoma, tended to have AR and PSA negative, however, in adenocarcinoma with neuroendocrine differentiation, AR was often positive and PSA expression was weakened or negative." (PMID 33598420, 2020). "However, NEPC is an AR‐negative and PSA‐independent small cell carcinoma that results from ADPC histological transformation." (PMID 34240817, 2021).